RAC1 (Rac family small GTPase 1)
Diseases named in the same sentence as RAC1 in open-access papers (continued):
Sharing a sentence is not in itself a finding about the gene and the disease.
tumor (continued). "However, the upregulated genes on chromosome 7 did include the RAC1 (Rac family small GTPase-1) gene, which has known roles in promoting tumour development and metastasis, and thus would merit investigation for potential involvement in the poor outcome of this group of patients." (PMID 36175618, 2022). "Thus, this system might be likely to reflect the activation of endogenous Rac1 mainly in the patients’ tumor tissues, although activation of other Rac members, such as Rac2 and Rac3 and/or Cdc42 cannot be ruled out." (PMID 35110666, 2022). "Interestingly, we found that CSDE1 at upregulated levels could act as an oncogene to regulate tumor cell growth, migration, and invasion by modulating the transcription of RAC1, a well-known proto-oncogene." (PMID 35490208, 2022). "Its family members, including ras-related C3 botulinum toxin substrate 1 (Rac1), ras homolog family member A (RhoA), and cell division cycle 42 (Cdc42), are engaged in the regulation of the morphology, cell-matrix adhesion, and cytoskeletal reorganization of tumor cells." (PMID 36230880, 2022). "Thus, it is important to evaluate the spatial activation of intrinsic Rac1/Cdc42 in tumor tissues." (PMID 35110666, 2022). "Moreover, actin nucleation and/or polymerization inhibition, for example targeting ARP2/3 or formins, could be used in the treatment of RAC1 mutant tumours." (PMID 34827551, 2021). "Therefore, intracellular mature IL-37 may be considered as a potential therapeutic agent against Rac1 activity and consequent tumor progression." (PMID 34248996, 2021). "Therefore, targeted inhibition of Rac1 in tumor cells may be a way to prevent immune escape, and may also be used as immune checkpoint inhibitors (ICIs)." (PMID 34079763, 2021). "However, more importantly, MIIP as a tumor suppressor attenuates Rac1." (PMID 32443784, 2020). "Taken together, we can conclude that 1A-116 is a PPI inhibitor able to selectively bind to W56 residue in Rac1 protein structure and may represent a suitable therapeutic agent for different types of neoplasms as well as pre-malignant disorders involving hyperproliferative phenotypes." (PMID 32351958, 2020). "Moreover, RAC1 expression positively correlates with tumour stage." (PMID 33298895, 2020). "Therefore, Porf-2 may inhibit tumor cell migration through the inactivation of Rac1 via the GAP domain, followed by the down-regulation of MMP-2/9." (PMID 32676454, 2020). "Therefore, as a part of the RhoGAP family, Porf-2 may suppress tumor cell migration through the inactivation of Rac1 via its GAP domain." (PMID 32676454, 2020). "However, several lncRNAs act as tumor-suppressing genes, which are generally lowly expressed in tumor tissue and suppress tumor proliferation or metastasis via repressing Rac1 by unknown mechanisms." (PMID 31248165, 2019). "Finally, we investigated whether blockade of the SUMO pathway with GA affected the activation of RAC1 in these MDA-MB-231 cell-derived tumours." (PMID 31578236, 2019). "Nuclear accumulation of RAC1 increases nuclear plasticity leading to a depletion of cytoplasmic, active RAC1 with a concomitant increase in RhoA signaling driving actomyosin-mediated cell shape changes; the two properties combine to enhance the tumor cell’s invasiveness." (PMID 31027363, 2019). "Thus, RAC1 plays a tumor‐promoting role in the progression and development of ESCC." (PMID 31314174, 2019). "Moreover, Rac1 has been shown to have an important role in tumor cell migration." (PMID 31338333, 2019). "Moreover, TIPE2 acts as a tumor suppressor by inhibiting Rac1 related signaling." (PMID 30186591, 2018). "Additionally, overexpression of RasV12 together with the actin-cytoskeletal genes, RhoGEF2, Rac1, or activated alleles of Rho1 (Rho1V14), can initially induce varying degrees of non-cell-autonomous tissue growth; however tumour growth predominates over time." (PMID 29693007, 2018). "Moreover, TIPE2 serves as a tumor suppressor via inhibiting the activation of Rac1." (PMID 30186591, 2018).
tumor (continued). "Moreover, a potential functional antagonism may be displayed by RAC1b versus RAC1 in controlling TGF-β signaling in conjunction with appropriate changes in relative activities during tumor progression." (PMID 28499439, 2017). "Importantly, in various tumor cells, RhoA and Rac1 expression and/or activity is increased." (PMID 28419128, 2017). "Although hypoxic conditions have been shown to increase tumor cell motility and aggressiveness through the activation of small GTPases, the cell-type dependence of the expression and activation of RhoA, cdc42 or Rac1 is unknown." (PMID 28562340, 2017). "In our previous study, we characterized a mycoplasma-derived highly conserved 240 amino acid small GTPase-like polypeptide (SGLP) that enhances phosphorylation of the signal transducer and activator of transcription 3 (STAT3) by activation of Rac1 and therefore might promote tumor growth." (PMID 28549350, 2017). "Therefore, it is likely that the known role of Rac1 in the maintenance of cell polarity could be an important element of its tumor suppressing function." (PMID 27506937, 2016). "In the present study, we found that TIPE2 suppresses tumor invasion and angiogenesis in a Rac1 dependent manner and it also serves as a novel biomarker for prediction of tumor metastasis, suggesting forced TIPE2 expression might be a novel strategy for the treatment of NSCLC." (PMID 27556698, 2016). "In addition, the FilGAP/Rac1 axis may serve as an important regulator of tumor progression in GBMs, probably through alteration of cell morphology." (PMID 27790861, 2016). "Rac1 activation could also directly activate JNK pathway leading to tumor progression." (PMID 27629044, 2016). "Unregulated Rac1 activity has been associated previously with oncogenic transformation, especially with cytoskeletal disarray, loss of cell polarity, and loss of cell adhesion, and thus we postulated that repression of Rac1 activity may be an additional tumor suppressive mechanism engendered by Rb." (PMID 26555075, 2015). "We propose that the Rho-ROCK-MLCP pathway may be specifically upregulated in tumor cells as they encounter certain extracellular cues (such as compliant environments) that prompt the downregulation of Rac1 signaling along with a concomitant up-regulation of RhoA activation." (PMID 26458510, 2015). "Thus, based on our in vitro and in vivo observations, we speculate that tumor-produced VEGF activates Rac1, resulting in increases of permeability and consequent metastasis of tumor cells to lung in hematogenously metastatic animal model." (PMID 25991673, 2015). "Rac1 activity may therefore represent a novel target for the control of tumor metastasis in vivo." (PMID 25888632, 2015). "However, since both Cdc42 and Rac1 signaling contribute to cellular transformation and tumor progression, inhibition of several GTPases could prevent bypassing of the blocked pathways and might constitute a therapeutic advantage." (PMID 24040362, 2013). "Although Rac1-activating mutations are newly discovered and described via exome sequencing in melanoma tissue, to date there are no reports of these mutations in other tumor types including GB." (PMID 24109588, 2013). "Among them, EGFR(7p11.2), TWIST1(7p21.2), RAC1(7p22), MTDH(8q22.1), CCNE2(8q22.1), TNFRSF11B(8q24) and GRB2(17q25) might be good candidates, as they are reportedly associated with invasiveness and metastasis of tumor cells." (PMID 23457519, 2013). "In this study we therefore asked whether growth inhibition and cell migration (as in vitro correlates of tumour growth and metastasis) are controlled differentially by Smad2 and Smad3 and whether Rac1 impacts on differential activation of both R-Smads by TGF-β1." (PMID 21624123, 2011).
tumor (continued). "Our findings will facilitate further research on the status of Rac1 activity in human tumors and will help to define the tumor types of the patient population that could potentially benefit from therapies targeting Rac activation or downstream effector signaling pathways." (PMID 21358804, 2011). "However, whether Rac1 contributes to human NSCLA tumor growth and/or metastasis, particularly if Rac1 plays a role in regulating CSCs, requires further investigation." (PMID 21347385, 2011). "Therefore, the Rac1-Pak1 pathway might be a potential therapeutic target for the prevention of tumor invasion and metastasis by inhibition of this signaling pathway." (PMID 20426825, 2010). "However, our loss and gain of function studies indicate that p190B has pro-tumorigenic actions and that it may facilitate tumor formation and progression in part by modulating Rac1 activity." (PMID 20860838, 2010). "Activated GTP-bound Rac1 (Rac1 activity) plays a key role in activating downstream effectors known as Pak (21-activated kinase), which are key regulators of cytoskeletal remolding, cell motility, and cell proliferation, and thus have a role in both carcinogenesis and tumor invasion." (PMID 20426825, 2010). "Primary tumors with LVI(+) and lymph node metastasis showed an increase of Rac1 activity and Pak1 expression, while metastatic lymph node tissues showed higher Rac1 activity and Pak1 expression than normal lymph nodes, indicating that Rac1 and Pak1 are involved in tumor metastasis." (PMID 20426825, 2010). "ARL4C promotes tumor survival and migration through the RAP1/PI3K-Akt/mTOR signaling loop and the RAC1/EMT signaling axis, and sustains its expression via deubiquitinase-mediated stabilization, thereby forming a positive feedback loop." (PMID 41328352, 2026). "The RAS protein family, known for its role in cell signaling, can influence cell death, proliferation, and metabolic stress responses through the Raf-1/MEK/ERK and Rac1/MKK7/JNK pathways, which in turn modulate tumor progression." (PMID 41040515, 2025). "By analyzing the spatial distribution of EPCAM expression, RAC1 expression, and B cell regions, we found that RAC1 is strongly co-localized with EPCAM and B cells are mainly distributed in non-tumor core regions and tumor margin areas." (PMID 39898257, 2025). "For instance, disrupting protein prenylation, a downstream process of the mevalonate pathway, can impair oncogenic signaling, reduce tumor cell proliferation, and enhance immunogenicity by interfering with RAS or RAC1 function." (PMID 41339438, 2025). "To investigate the relationship between RAC1 expression and immune cell infiltration, we employed the CIBERSORT algorithm to analyze 22 types of immune cell infiltration scores within the tumor microenvironment." (PMID 39898257, 2025). "To further investigate the potential relationship between RAC1 and B cell infiltration, we employed xCell, TIMER, and Quantiseq to calculate infiltration scores of immune subsets in the tumor microenvironment." (PMID 39898257, 2025). "We found that Rac1-GTP levels were high in RD cells, potentially promoting tumor cell proliferation and migration." (PMID 40076757, 2025). "Similar to what was observed on the transcription level, GTPase-related pathways—notably, those involving RAC1, RAC3, and RAS proteins—were significantly enriched in the tumor cells." (PMID 40724880, 2025).
tumor (continued). "Other Rac1-targeting compounds, including EHT 1864, Z62954982, and 1D-142, were all reported to inhibit Rac1 in tumor models." (PMID 41188920, 2025). "These SEs showed strong correlations with key genes involved in immunosuppression and tumor progression, including SPP1, RAC1, CTSC, and SMS." (PMID 40725473, 2025). "Downregulation of EPS8, SOS1, or RAC1 in PDAC cells suppresses cell movement but also increases integrin αVβ6-dependent TGFβ activation through Rho activation, which has both tumor suppressing and activating effects." (PMID 39354505, 2024). "PF reversed the RAC1 overexpression‐mediated increase in tumor growth; moreover, PTX combined with PF increased the effects of PF alone on the RAC1 overexpression group." (PMID 39224538, 2024). "We knocked down PAK4 in the RAC1‐overexpressing OC cell lines ES‐2 and A2780 and found that PAK4 knockdown reversed the tumor‐promoting effects of RAC1 overexpression." (PMID 39224538, 2024). "Multiple investigations have indicated that the activation of Rac1 is prompted through its interaction with ITGB6, one of its downstream effectors, thereby augmenting the migratory and invasive capabilities of tumor cells." (PMID 38344200, 2024). "Intriguingly, TRIP12 inhibition blocked HACE1-driven RAC1 ubiquitination and mitigated the inhibitory effects of HACE1 on ESCA cells, alleviating tumor growth in the tumor-bearing nude mouse model." (PMID 38706891, 2024). "Most importantly, TRIP12 inhibition blocked HACE1-driven RAC1 ubiquitination and mitigated the inhibitory effects of HACE1 on ESCA cells, alleviating tumor growth in the tumor-bearing nude mouse model." (PMID 38706891, 2024). "Interestingly, tumors derived from animals treated with Rac1 inhibitor showed an increased number of immune cell infiltrates suggesting that Rac1 inhibition could be acting through different mechanisms, including immune escape mediated by tumor microenvironment." (PMID 39513883, 2024). "The tumor driver CTNND1 is the key component involved in cell–cell adhesion and Rac1, Cdc42, and Ras homolog gene family member A (RhoA) activation and has been reported to repress the migration and invasion of tumor cells." (PMID 39338204, 2024). "To further confirm the antimetastatic potential of Rac1 inhibition on 5-FU resistant CRC, we performed an intrasplenic cell injection, noting that 1A-116 treatment drastically reduced spleen tumor formation and resistant cell dissemination to the liver." (PMID 39513883, 2024). "We observed significantly higher expression of METTL16, ITPR1, CAPN2, ITGA3, RAC1, ITGA6, and CHMP28 in tumor samples (P<0.05)." (PMID 39434688, 2024). "We previously found that intracellular mature IL-37b can bind directly to and inactivate Rac1 by targeting its CAAX motif of the C-terminus, thereby inhibiting tumor cell migration and tumor metastasis." (PMID 38907105, 2024). "Meanwhile, RNA-seq and IP experiments indicated that ABI2, acting as a crucial factor of tumor suppression, can significantly inhibit PI3K/Akt signaling pathway via the interaction with Rho GTPase RAC1." (PMID 38937761, 2024). "We focused on GBM and lung tumors, as they are currently the only tumor types in which it has been provided evidence of an indirect CBX3-mediated regulation of EGFR and RAC1, respectively." (PMID 37633946, 2023). "POTEE activates Rac1 in the invadopodium by recruiting TRIO-GEF (triple functional domain protein), and it induces tumor cell proliferation and metastasis in vitro and in vivo." (PMID 38098337, 2023). "It was found that miR-331-3p inhibits Rac1/PAK1/β-catenin by targeting Vav2, thereby inhibiting EMT and the subsequent invasion and migration of tumor cells." (PMID 37049739, 2023).
tumor (continued). "IFN-γ activates the RhoGDI2/Rac1/NF-κB pathway in tumor cells to reduce the production of the pro-tumor cytokine CXCL8, promoting tumor apoptosis and reducing CXCR2+ M2 macrophages." (PMID 37275859, 2023). "Through β-catenin, Rac1/PAK1 can facilitate EMT, which is an essential condition for the invasion and metastasis of tumor cells." (PMID 37049739, 2023). "We found that MAP2K6, MAP3K5, MAP3K9, MAP3K12, RPS6KA2, RPS6KA5, and STAT1 were lowly expressed in tumor tissues; However, NFKB1, RAC1, SHC1, and TRAF2 are highly expressed compared to normal tissues." (PMID 36969076, 2023). "In many tumor types shallow deletion and low-level copy gain for CBX3 and RAC1, and in a lesser extend for EGFR, results in a proportional manner respectively significantly lower and higher mRNA levels of the corresponding genes." (PMID 37633946, 2023). "To investigate the differences in therapeutic outcome when targeting Rac1P29S+ MC703-FSG tumors with either Rac1- or Rac2-specific T cells, we monitored the human TCR-transduced HHD+ T cells after transfer into tumor-bearing mice in the second experiment." (PMID 36875127, 2023). "Both the GEFT and DEP domains containing 1B (DEPDC1B) can interact with Rac1 to activate Rac1 and downstream PAK1, thus promoting EMT and enhancing the invasion and migration of tumor cells." (PMID 37049739, 2023). "Significant changes have been detected in the tumor microenvironment pathway including genes MMP19, MMP24, and CSF2, as well as PLAU, BCL2, TIAM1 and Rac1." (PMID 38003292, 2023). "Therefore, in addition to Rac1, the Rap1 GTPase plays a key role in the signalling pathways mediating CA induction of an invasive phenotype in control breast epithelial cells, and this points to Rap1 inhibition as a potential new therapeutic option for many CA tumours." (PMID 37772773, 2023). "Latency analysis of palpable tumor formation revealed a significant delay in heterozygous Rac1flox/+;MMTV-NIC mice compared with Rac1+/+;MMTV-NIC mice." (PMID 36599922, 2023). "RAC1 can promotes the invasiveness and migration ability of LUAD cells and similar results were found in other tumor cell lines." (PMID 37202394, 2023). "Rac1 SUMOylation occurs during epithelial-mesenchymal transition (EMT), and it is required for tumor cell migration and invasion." (PMID 38098337, 2023). "Taken together, LIMK1/cofilin is a crucial downstream signaling pathway of Rac1/PAK1 for regulating the rearrangement of actin cytoskeleton and lamellipodia extension of tumor cells." (PMID 37049739, 2023). "High expression of RAC1, RHOA, CDC42, and VEGFB were identified in metastatic subgroups, compared to primary tumor and normal lung epithelia clusters." (PMID 37202394, 2023). "Consistent with the role of RAC1, PAK1, and CDC42 in regulating inducible macropinocytosis, analysis of the TCGA dataset revealed higher expression of RAC1, PAK1, and CDC42 in HCC tissues than in non-tumor lesions." (PMID 35287706, 2022). "We used Ki67 staining to further confirm the differences between treatments in tumor proliferation, and Western blot showed that TBOPP abolished metformin-mediated RAC1 activation in the NRASG12V/shP53-induced orthotopic HCC model." (PMID 35217990, 2022). "In order to explore the function of Rac1, we collected HCC patients' tumor tissues and detected the level of Rac1." (PMID 35847360, 2022). "RhoGAPs thus inactivate Rho GTPases (Rac1, CDC42) and have generally been presumed to act as tumor suppressors." (PMID 36168627, 2022). "Therefore, Rac1 inhibition could significantly suppress tumor growth." (PMID 35031595, 2022). "The Rac1 knockdown improved the tumor prevention capabilities of DADS; in contrast, the overexpression of Rac1 counteracted its effects." (PMID 36071845, 2022).